JAK2 (Janus kinase 2)
Diseases named in the same sentence as JAK2 in open-access papers (continued):
Sharing a sentence is not in itself a finding about the gene and the disease.
Splenomegaly (continued). "In MPN, preclinical data strongly supports the effect of HDACi inhibiting proliferation and inducing apoptosis in JAK2 mutated cells, normalizing splenomegaly and blood counts in JAK2 mutant knock-in mice and promoting proteasome mediated JAK2 degradation by disrupting HSP90 chaperone function." (PMID 30304859, 2018). "Here, we report two elderly MF patients with massive splenomegaly and a JAK2 V617F mutation." (PMID 27840748, 2016). "However, in this case, fedratinib therapy (200 mg a day owing to JAK2 pathogenic gene variants) was continued because, initially, the association between fedratinib and uveitis was unclear, and fedratinib was effective for splenomegaly." (PMID 40276423, 2025). "A 60‐year‐old female had a diagnosis of JAK2‐positive primary MF made following the discovery of mild splenomegaly on imaging." (PMID 40123795, 2025). "For example, these JAK2-V617F transgenic mice develop erythrocytosis and thrombocytosis as adults (10–12 weeks of age) with a gradual onset of splenomegaly and extramedullary hematopoiesis." (PMID 40076747, 2025). "While some patients exhibited a decrease in leukocyte and platelet counts, splenomegaly, and pruritus, only minor decreases in JAK2 V617F burden were identified." (PMID 40699626, 2025). "Although JAK2 inhibitors have a good efficacy in reducing splenomegaly, the presence of a significant proportion of non‐responder patients underlines the need to explore the cellular mechanisms responsible for the EMH onset." (PMID 40690545, 2025). "JAK-inhibitor treatment showed a response of splenomegaly (4/5) and symptoms (5/5), whereas the JAK2 V617F VAF remained unchanged in most patients (#6, #8, #10)." (PMID 40681596, 2025). "In patient #5, splenomegaly and symptoms improved, but thrombocytosis and JAK2 V617F VAF remained unaffected on 30 mg total daily dose of ruxolitinib, which was therefore increased to 40 mg daily." (PMID 40681596, 2025). "The patient’s presentation with SVT, splenomegaly, and a history of unprovoked pulmonary embolism aligns with reports of latent MPNs unmasked by thrombotic events, with JAK2 V617F detected in 32.7% of SVT cases and 49% of idiopathic SVT." (PMID 40605890, 2025). "This case report describes a 33-year-old woman presenting with recurrent splanchnic vein thrombosis, splenomegaly, and a history of unprovoked pulmonary embolism, found to have a JAK2 V617F-positive latent myeloproliferative neoplasm." (PMID 40605890, 2025). "Mice studies have shown that the antioxidant N-acetylcysteine can reduce splenomegaly, JAK2-mutant HSCPs, and normalize blood parameters." (PMID 41268532, 2025). "Ruxolitinib is a type-1 JAK1/JAK2 inhibitor that has been used for the therapy of MF-related splenomegaly and symptoms for nearly 15 years." (PMID 39831987, 2025). "For instance, targeted inhibitors of JAK2, such as ruxolitinib, have emerged as cornerstone treatments in JAK2-positive cMPNs, providing symptomatic relief and reducing splenomegaly." (PMID 39685591, 2024). "Although there is well established association between JAK2 positive MPN and thrombotic events, pre‐hepatic portal hypertension presenting with complications such as ascites, SBP and splenomegaly are infrequently evaluated for JAK2 mutations." (PMID 37405042, 2023). "The JAK2 inhibitor ruxolitinib controls not only constitutional symptoms and splenomegaly, but also lowers CRP levels and increases albumin concentration." (PMID 36900271, 2023). "To explore potential determinants of engraftment, we evaluated MF disease characteristics including primary vs secondary MF, driver mutations in JAK2, CALR and MPL, prognostic risk group, splenomegaly and BM fibrosis as well as ruxolitinib therapy before HCT." (PMID 37637037, 2023). "The JAK2 inhibitor, ruxolitinib, is efficacious in reducing symptoms and splenomegaly in patients with PMF." (PMID 35455686, 2022).
Splenomegaly (continued). "Ruxolitinib is known to target JAK1 and JAK2 and inhibits serum inflammatory cytokine secretion, thereby reducing symptoms such as fever, night sweats, itching, and fatigue, and splenomegaly." (PMID 35328626, 2022). "ERK1/2 deficiency significantly enhanced therapeutic efficacy of concomitant JAK2 inhibitor treatment regarding erythrocytosis, splenomegaly, fibrosis and clone control." (PMID 34480104, 2021). "Ruxolitinib, fedratinib or JAK2 inhibitors in development provide benefits including reduction of splenomegaly and symptoms." (PMID 34480104, 2021). "JAK2 inhibitor therapy holds benefits particularly in regard to splenomegaly and symptom control, but it has become clear that disease-modifying activity is limited with continued clonal evolution and responses restricted to finite periods." (PMID 34480104, 2021). "Ruxolitinib is a potent JAK1/JAK2 inhibitor approved for the treatment of MF-related splenomegaly or symptoms in adults with PMF, PPV-MF, or PET-MF." (PMID 34017073, 2021). "We used a MPLW515L MPN model characterized by extensive BM fibrosis, splenomegaly, leukocytosis and thrombocytosis, which shares the typical activation of JAK2 and MAPK signaling seen in Jak2V617F-driven models." (PMID 34480104, 2021). "Past studies on NTDT and TDT animal models revealed that JAK2 inhibition improved ineffective erythropoiesis and reversed splenomegaly, thereby paving a path for JAK1 and JAK2 inhibitors." (PMID 34754662, 2021). "PV patients carrying a JAK2 V617F mutation had higher peripheral blood WBC counts (P = 0.006) and PLT counts (P = 0.001) and were more prone to splenomegaly (P < 0.05)." (PMID 32095159, 2020). "One clinical trial did also link another JAK2 inhibitor with decreased inflammatory cytokines, reduced splenomegaly and the exertion of immunomodulatory effects (ClinicalTrials.gov Identifier: NCT01437787)." (PMID 32604862, 2020). "Development of CML must be considered in cases of JAK2-positive MPD with CML-like features such as leukocytosis or progressive splenomegaly years after clinical stability." (PMID 30803277, 2019). "The oral Janus kinase (JAK) 1/JAK2 inhibitor ruxolitinib has been shown to improve splenomegaly, symptom burden, and overall survival in patients with intermediate-2 or high-risk MF compared with placebo or best available therapy (BAT)." (PMID 29544547, 2018). "A recent study showed that absence of JAK2 in a CML-CP model drastically accelerated disease development with increased numbers of WBC counts and severe splenomegaly, suggesting that JAK2 inhibits the progress of CML." (PMID 27233483, 2016). "JAK2 inhibition induced a correction of splenomegaly, leucocytosis and microcytosis in all three MPN models." (PMID 26176817, 2015). "In this study, once-daily dosing with the JAK2-selective inhibitor fedratinib led to clinically significant and durable improvements in splenomegaly and symptom burden in patients with intermediate-2 or high-risk MF." (PMID 26252788, 2015). "We demonstrated that simultaneous inhibition of JAK2 and PI3K signalling pathways led to significantly delayed splenomegaly in mice inoculated with Ba/F3 TpoR JAK2 V617F cells." (PMID 24251790, 2013). "We have demonstrated that intermittent dosing of a JAK2 inhibitor can effectively normalize erythroid progenitor populations and thereby effectively treat conditions of polycythemia and splenomegaly in mouse models of PV." (PMID 22623993, 2012). "This review will discuss the therapies (apart from bone marrow transplant) currently used to treat splenomegaly and splenomegaly-related symptoms in patients with MF and the potential role of the JAK2 (as well as JAK1/JAK2) inhibitors." (PMID 22852872, 2012). "Notably, pacritinib, a JAK2 inhibitor that also targets IRAK1, has been linked to a reduction in splenomegaly and alleviation of associated symptoms." (PMID 41268532, 2025).
Splenomegaly (continued). "Regardless of driver mutations, patients with splenomegaly and symptoms are generally treated with JAK2-inhibitors, most commonly ruxolitinib." (PMID 39831987, 2025). "At 24 months, splenomegaly was present in 12 of 28 patients (42.9%), again without significant differences between JAK2- and CALR-mutated cohorts (p > 0.99)." (PMID 41463191, 2025). "He had JAK2‐positive disease that was diagnosed 2 years prior when he presented with splenomegaly." (PMID 40123795, 2025). "Apo-transferrin (apo-Tf), hepcidin agonists, JAK2 inhibitors, Tmprsso inhibitors, and activin receptor II (ActRII) ligand traps hold promise for improving iron overload management, averting splenomegaly and thrombosis, and decreasing the need for transfusions in individuals with ß-thalassemia." (PMID 39449307, 2024). "In addition to elevated blood counts, FERM‐JAK2 also induced a profound splenomegaly with a median spleen weight of 476 mg, compared to 292 mg for JAK2‐V617F+ and 113 mg for empty vector control mice." (PMID 38104968, 2024). "However, since the introduction of ruxolitinib, an oral Janus kinase (JAK) 1/JAK2 inhibitor that effectively reduces splenomegaly in 42% of patients and improves symptoms, the indication for splenectomy is highly improbable." (PMID 39210059, 2024). "Hepatomegaly and splenomegaly were comparable between patients with and without the mutation of JAK2 p.V617F." (PMID 38274463, 2023). "As in the antibody model, JAK2 mutant mice developed pronounced splenomegaly, which was not accentuated on the mutated Sirpα background." (PMID 37095207, 2023). "In our study, although numerically more splenomegaly was observed in patients with JAK2, CALR, or MPL mutations, this difference was not statistically significant." (PMID 35444868, 2022). "This will be a double-blind, placebo-controlled study for those at least 18 years of age with intermediate-2 or high-risk MF with splenomegaly or MF-related symptoms and no prior treatment with JAK2 inhibitors." (PMID 34667663, 2021). "ET patients carrying a JAK2 V617F mutation had higher peripheral blood WBC counts (P = 0.001), higher Hb concentrations (P = 0.001), and lower PLT counts (P = 0.037) and were more prone to splenomegaly and abnormal endogenous coagulation (P < 0.05)." (PMID 32095159, 2020). "Risk factors for survival after transplant comprise high transfusion requirement, massive splenomegaly, non-sibling donor type, advanced age, JAK2 V617F-mutated status, constitutional symptoms, and HLA-mismatched donor." (PMID 31534197, 2020). "IMG7289 (bomedemstat), an LSD1 inhibitor, reduced splenomegaly, normalized blood counts, and prolonged survival in the Jak2 V617F murine model, which has led to the clinical evaluation of bomedemstat as a second-line agent in PV and ET (NCT04254978) (NCT04262141)." (PMID 33267911, 2020). "The JAK2 inhibitor ruxolitinib reduces splenic haematopoiesis but does not reverse MF in the Gata1low mice, and ruxolitinib is currently approved by the Food and Drug Administration (FDA) only for palliation of splenomegaly and MF‐associated symptoms." (PMID 29971909, 2018). "This 36-year old pregnant patient with acute MF did not present with the cardinal signs of MF, i.e., her spleen was not palpable (slight splenomegaly on CT) and JAK2 mutational status was normal, thereby ruling out primary MF." (PMID 29020927, 2017). "Meanwhile, the JAK2-/CALR+ group had higher rates of splenomegaly than did the JAK2-/CALR- group." (PMID 27486987, 2016). "In addition, as expected, myeloproliferative features such as CMML-MP variant, leukocyte count or presence of splenomegaly, correlated with genes involved in cell signaling, such as NRAS and JAK2." (PMID 27486981, 2016). "The discovery of Jak2 as an important mediator of IE and splenomegaly in β-thalassemia suggests that the use of small organic molecules to inhibit Jak2 could be beneficial in reducing IE and splenomegaly." (PMID 20508726, 2010).
Splenomegaly (continued). "In all of these studies, it was clear how hyperactivation of Jak2 contributes to a massive increase in the erythropoietic activity and a huge expansion of the erythron with related splenomegaly, a phenotype that is interestingly similar to what is observed in β-thalassemia." (PMID 20508726, 2010). "In this scenario, the therapeutic treatment of β-thalassemia patients with Jak2 inhibitors could be useful as it would target the two major complications of this pathology, IE with its related splenomegaly and the massive iron overload." (PMID 20508726, 2010). "At autopsy, JAK2 V617F recipients had significant splenomegaly, particularly in Balb/c mice (mean spleen weight 0.58±0.19 g versus 0.08±0.01 for Balb/c recipients of JAK2 WT-transduced BM, P = 0.0023 by unpaired t-test), but no involvement of lymph nodes or thymus, and no pulmonary hemorrhages." (PMID 17183644, 2006). "However, after the discovery of dysregulation of the Janus kinase (JAK) pathway, most commonly JAK2 V617F mutation, in over half of MF patients, targeted therapies with JAK inhibitors have demonstrated improvements in splenomegaly, burden of symptoms, and a potential gain in overall survival." (PMID 30997748, 2019). "However, there was not a relationship found between the presence of JAK2 mutation and splenomegaly in cases with BCR‐ABL negative CMDs in a study from Turkey." (PMID 29732039, 2018). "It gives clues on the mechanisms on how JAK2 inhibition may modulate platelet counts, block marrow fibrosis and osteosclerosis and prevent mobilization of early neoplastic cells in extramedullary sites decreasing splenomegaly." (PMID 26176817, 2015). "Disease progression is assessed through symptoms and markers like increased JAK2 VAF, clonal evolution, splenomegaly, circulating blasts, cytopenias, reduced response to therapy, or higher phlebotomy needs." (PMID 41091181, 2025). "As expected, mice transplanted with Jak2 V617F cells developed characteristic MPN features, including splenomegaly, increased white blood cell (WBC), red blood cell (RBC), and platelet counts." (PMID 38060311, 2024). "Combined pharmacologic JAK2/ERK1/2 inhibition with ruxolitinib and ERK inhibitors reduced proliferation of Jak2V617F cells and corrected erythrocytosis and splenomegaly of Jak2V617F MPN mice." (PMID 34480104, 2021). "We found that dual JAK2/ERK1/2 inhibition by 60 mg/kg ruxolitinib bid and 75 mg/kg LTT462 qd abrogated splenomegaly and corrected leukocytosis and thrombocytosis." (PMID 34480104, 2021). "In a previous study, we have demonstrated that simultaneous inhibition of JAK2 and PI3K signaling pathways led to delayed splenomegaly in mice inoculated with Ba/F3-MPL/JAK2V617F cells." (PMID 28903325, 2017). "Discovery of the JAK2 V617F mutation prompted the development of clinical trials using JAK2 inhibitors; overall, these agents have resulted in meaningful symptomatic improvements and reductions of splenomegaly that were otherwise not achievable with conventional therapy." (PMID 26316489, 2015). "We also found a differential expression of PRV1 according to JAK2 V617F status and a correlation between PRV1 expression and platelet count in ET and PMF patients, as well as splenomegaly." (PMID 22300941, 2012). "Clinical data on selective inhibitors of JAK2 or JAK1 and JAK2 are promising and suggest that they improve certain MPN-related symptoms and constitutional signs, as well as reduce splenomegaly." (PMID 22830345, 2012). "Between the time of diagnosis and the time of ruxolitinib start, clinical and hematological features worsened in both JAK2 and CALR cohorts, with progressive increase of leukocytes, blast counts, splenomegaly and symptoms, and decrease of hemoglobin levels and platelet counts." (PMID 39831987, 2025). "Lastly, we conducted a subgroup analysis to examine the effect of cytoreduction in high-risk patients, (JAK2 mutated, elevated WBC count, absence of splenomegaly)." (PMID 40074852, 2025).
Splenomegaly (continued). "Multivariate analysis included the variable type of driver mutation (JAK2 or CALR), the detection of non-driver mutations, WBC, PLT and LDH counts, patient age, gender, left shift, splenomegaly, and fibrosis grade." (PMID 41463191, 2025). "The appearance of constitutional symptoms, splenomegaly, PTL increase, RBC increase or cytopenia in patients with CML in MR should lead clinicians to rule out a coexisting Ph-negative MPN and mutations of JAK2, MPL, CALR should be evaluated." (PMID 38282677, 2023). "Similar to ruxolitinib/LTT462, dual JAK2/ERK1/2 inhibition by 60 mg/kg ruxolitinib bid and 30 mg/kg MK-8353 bid enhanced MPN phenotype correction in the MPLW515L model including reduction of splenomegaly, leukocytosis and thrombocytosis." (PMID 34480104, 2021). "Recently, JAK2 activation in MPL-mutant cells was found to support the CXCL12/CXCR4 pathway and activate downstream JAK-STAT, PI3K/AKT, and RAS/MAPK activation pathways, leading to the expansion of malignant clones, EMH, and splenomegaly in MF patients." (PMID 29562644, 2018). "Significantly elevated odds ratios for the occurrence of thromboembolism were found for a diagnosis of post-PV-MF and splenomegaly, but not the other subtypes, JAK2 V617F, leukocytosis, or thrombocytosis." (PMID 26944254, 2016). "In both strains, JAK2 V617F, but not JAK2 WT, induced non-fatal polycythemia characterized by increased hematocrit and hemoglobin, reticulocytosis, splenomegaly, low plasma erythropoietin (Epo), and Epo-independent erythroid colonies." (PMID 17183644, 2006). "A number of JAK2 inhibitors have been under clinical trials for MPNs, and only the JAK1/JAK2 inhibitor ruxolitinib has been in clinical use in general practice for PMF or PV mainly to reduce splenomegaly and various symptoms and possibly to improve survival of these patients." (PMID 32050632, 2020). "A subset of recipient mice transplanted with Eμ-Crlf2 FLCs expressing Jak2 mutants (Jak2R683G and Jak2P933R) succumbed to disease with outgrowth of GFP+ populations in the spleen and bone marrow and elevated peripheral white blood cell (WBC) counts and/or splenomegaly." (PMID 29907650, 2018). "Also in Jak2V617F settings, ruxolitinib/MK-8353 showed comparable effects in normalizing erythrocytosis and splenomegaly as seen with ruxolitinib/LTT462, thus credentialing combined JAK2/ERK1/2 inhibition as a valid approach to enhance the corrective potential of JAK2 inhibitor therapy for MPN." (PMID 34480104, 2021).